KRT5 (keratin 5)
Diseases named in the same sentence as KRT5 in open-access papers (continued):
Sharing a sentence is not in itself a finding about the gene and the disease.
tumor (730 papers, 2004 to 2026). "The expression of cytokeratin 5 is linked to the phenotype of cells undergoing the epithelial-mesenchymal transition, which is used by the tumour to gain migratory and invasive properties, thereby causing metastasis." (PMID 38300959, 2024). "Using an RU486-inducible keratin 5-driven Cre allele (K5-CrePR), the tumor suppressors Pten and Smad4 are specifically deleted in K5-positive basal epithelial cells in the salivary glands." (PMID 37474617, 2023). "Class 3 tumours show some of the gene expression characteristics associated with MIBC (KRT5+, KRT14+, CD44+, KRT20− and PPARG−)." (PMID 36928373, 2023). "Analyzing clinical data in a comprehensible manner, we found an association between higher tumor grade at diagnosis and overexpression of KRT5 in CTCs at V1, which is the gene that encodes CK5." (PMID 31817194, 2019). "Immunohistochemical analysis revealed that the tumor cells were positive for protein kinase C, p63, cytokeratin 5/6 (CK 5/6) and EBV-encoded small RNA (EBER), whereas the cells were negative for CK 7 and thyroid transcription factor-1." (PMID 25789039, 2015). "There has been particular interest in the subgroup of basal-like tumours, which express many myoepithelium-associated genes, such as cytokeratin 5, and which are both cerbB2- and ER-negative and are associated with a poor prognosis." (PMID 18182985, 2008). "In our cohorts, significant enrichment of the genes involved in the keratinization and the formation of keratinized layers in tumor tissue (KRT5, KRT6A-C, KRT13-KRT17, KRT19) and genes associated with the regulation of cell division (FOXM1, p63) was identified." (PMID 38398111, 2024). "Therefore, to characterize early tumorigenesis from tumor-prone Krt5+ foregut basal progenitors and to determine their relative tumor susceptibility, we used low-dose tamoxifen treatment (1 day of 0.2 mg tamoxifen by i.p. injection) and analyzed the results." (PMID 31110179, 2019). "Note that these tumours arose from the same cell populations simultaneously expressing KRT5 and KRT14." (PMID 41507151, 2026). "Immunohistochemically, the tumor cells express cytokeratins, including the squamous cell lineage markers cytokeratin 5/6, p63, and p40." (PMID 40125228, 2025). "Co-immunofluorescence staining for EPCAM and KRT5 in subcutaneous tumours demonstrated an apparent continuum of cell states." (PMID 40468074, 2025). "AKP AtrxKO tumours contained significantly more KRT5+ cells than control tumours, and metastatic lesions were further enriched compared with subcutaneous tumours." (PMID 40468074, 2025). "Immunohistochemically, the tumor cells showed positive nuclear staining for P63 and P40, while cytokeratin 5/6 (CK5/6) showed positive cytoplasmic staining." (PMID 40013203, 2025). "Cytokeratin 5/6 (CK5/6) and P63 were only expressed in the tumor surface-coated squamous epithelium and in the myoepithelial cells of the glandular lumen, and S-100 protein (S-100) was only positive in myoepithelial cells." (PMID 40013097, 2025). "We then categorized patients based on VPS25 and KRT5 (tumor cell marker gene) expression into high-score and low-score groups." (PMID 40149859, 2025). "The atypical cells are positive for pan-cytokeratin, cytokeratin 5/6, and p63, which highlight the epithelial component of the tumor." (PMID 38952856, 2024). "Tumor of myoepithelial origin with tumor cells expressing the myoepithelial markers S-100, cytokeratin 5/6, P63." (PMID 39465766, 2024). "The cell was discovered to have traits resembling those of the original tumor tissue and to express calretinin, WT-1, and cytokeratin 5/6." (PMID 38200517, 2024). "In this space, the tumor cells were readily distinguishable from the remaining cells by the basal marker Keratin 5 or the expression of either the luminal marker GATA3 or other keratin proteins." (PMID 38499531, 2024). "Increased KRT5 expression is a diagnostic marker for BCC, indicating tumor origins in the skin’s basal cell layer." (PMID 39003418, 2024).
tumor (continued). "This study concluded that basal tumours with KRT5/6, p63, and KRT14 expression had a better response to chemotherapy, while luminal tumours with active PPAR expression and activating mutations in FGFR3 showed expression of KRT20, FOXA1, and GATA3." (PMID 39594166, 2024). "Along these lines, most of the Krt5-expressing tumor cells also co-expressed Krt8, with only a small percentage of cells exclusively expressing the basal marker." (PMID 36859337, 2023). "Cells with fully basal phenotypes in which only Krt5 was expressed were rare and only found in 9 out of 13 low-ER tumor cores." (PMID 36859337, 2023). "In order to trace the lineage of the MMTV-PyMT tumor cells, either Krt8 (luminal) or Krt5 (basal) specific, tamoxifen-inducible CreERT promoters were used to induce expression of GFP in an mTmG reporter mouse to label luminal or basal cells, respectively." (PMID 36859337, 2023). "As a tumour suppressor, KRT5 participates in the expression and regulation of cell cycle progression and DNA damage repair in normal cells." (PMID 37671092, 2023). "The KRT5 gene can regulate the formation of the cytoskeleton and venous invasion of cancer cells, and its low expression is related to tumor recurrence and metastasis." (PMID 37251946, 2023). "Luminal-like tumor cells were identified by Krt8 expression, whereas basal-like tumor cells were identified by either Krt5 or Krt14 expression." (PMID 36859337, 2023). "Consistent with our observations, they also found Krt5 expression to be restricted to the edges of the tumor." (PMID 36859337, 2023). "Cancerous squamous cell‐associated genes such KRT5, CDKN2A, and SERPINB3 were mainly enriched in the Stereo‐seq tumor areas, IGKC and IGLC2 were enriched in inflammatory areas, VIM in stromal areas, ADRA2A in blood vessels, and MUC5B in glands." (PMID 35986392, 2022). "Tumor cells can be divided into 4 different subtypes, including basaloid cells (KRT5, KRT14), myoepithelial cells (ACTA2, MYL), cycling cells (MKI67, TOP2A) and duct-like cells (KRT7, KRT19)." (PMID 35860547, 2022). "We next quantified expression levels of the basal (keratin 5, K5) and luminal (keratin 8, K8) lineage markers in the histological tumor sections." (PMID 36010633, 2022). "MMP10, 7, 13 and TIMP1 were reduced in cured mice compared to tumor bearing mice, while Krt5 and Cldn8 levels increased in cured mice." (PMID 34944584, 2021). "In the present study, high ERBB2 expression correlated significantly with an elevated KRT20 expression indicative of luminal tumours and with a lower KRT5 expression as a marker for basal tumours." (PMID 34073233, 2021). "As a result, the ER+ cancer sample was clustered with ER+ tumor cells (ESR1+, KRT18+, and KRT5−), KRT5+/EPCAM+ double-positive cells, cancer-associated fibroblasts (CAFs) (DCN+), macrophages (CD68+), KRT5+/EPCAM− cells, and endothelial cells (VWF+)." (PMID 34685653, 2021). "Targeting of Stk11 also led to the establishment of KRT5+/TTF1– tumors, indicating that loss of this tumor suppressor leads to the simultaneous development of NSCLC-SCC and NSCLC-ADC." (PMID 33738287, 2021). "The mRNA expression of CYP1A1 (p = 0.002), CCL20 (p = 0.047), p19 (p = 0.029), CCL19 (p = 0.013), IL-36γ (p = 0.0076), and IL-17 (p = 0.0035) was significantly decreased in tumor from AhR-(fl/fl) Krt5-(Cre) mice compared with wild type mice." (PMID 33178182, 2020). "To do this, we used a Krt5-tomato reporter mouse line to positively identify and trace the lineage fate of CK5high (basal cells) in normal and tumor-bearing bladders." (PMID 32439865, 2020). "The low-risk miRNAs from has-let-7 family (hsa-let-7c, hsa-let-7b) act as tumour suppressors through controlling cellular processes such as cell projection, cell proliferation, and cell development, involving the genes KRT5 and GABBR2." (PMID 32182819, 2020).
tumor (continued). "One tumor presented with high expression of different keratins, e.g. keratin 5 (KRT5, referred to as CK5 in IHC) in the NanoString analysis, shifting the SSP classification towards SqCC." (PMID 30914778, 2019). "When measuring the relative tumor fractions of these populations, it was observed that Wnt1-LateEx tumors contained a higher fraction of Krt5-positive cells (P=0.02) and Krt8/18-positive cells (P=0.001) than Wnt1-EarlyEx tumors." (PMID 31213486, 2019). "This study demonstrates the association of gastric acid stress with Cyclooxygenase-2-dependent tumor formation originating from tumor-competent Krt5+/Krt15+ foregut basal progenitor cells." (PMID 31110179, 2019). "The TMP panel included 7 proteins routinely used in diagnostic IHC including cytokeratins (KRT5 and KRT7), markers of stratified epithelia (P63), mesenchymal (Vimentin) and neuroendocrine (CHGA, SYP) differentiation, and primary tumour origin (TTF1)." (PMID 31537838, 2019). "Here, the authors show that gastric acid stress stimulates tumour formation from a defined tumour-competent Krt5 + /Krt15 + foregut basal progenitor cell population." (PMID 31110179, 2019). "They contained typical horn pearls, rarely displayed surface ulcerations and the tumor cells expressed keratin 5 (Krt5) and β4-integrin (Itgb4) in basal layers, and keratin 10 (Krt10) in upper layers when present." (PMID 31803622, 2019). "Key eligibility criteria were: basal-like BC (estrogen and progesterone receptor < 1%, HER2-negative, cytokeratin 5/6 or epidermal growth factor receptor positive by immunohistochemistry), tumor size > 2 cm or <2 cm with nodal involvement." (PMID 31398896, 2019). "Tumor levels of cytokeratin-5 (CK5) correlated positively with B Cell CLL/Lymphoma 6 (BCL6) in premenopausal women with hormone positive breast cancer." (PMID 31114446, 2019). "Taken together, this study demonstrates the significant contribution of physiological acid stress as a co-promoting factor in foregut tumor initiation from tumor-competent Krt5+/Krt15+ basal progenitor cells." (PMID 31110179, 2019). "Basal cells are considered potential cells of origin of LSCC, as they share certain markers with LSCC tumor cells, including cytokeratin 5 expression." (PMID 30642944, 2019). "Tumor expression profile included an upregulation of basal cell markers such as Krt5, Krt6, Krt14 and Krt1 as well as Cdh3 and Cd44." (PMID 31779626, 2019). "Patients diagnosed with more advanced tumor grades at metastases showed CTCs with high expression levels of KRT5 and low expression of E2F4 (p = 0.024)." (PMID 31817194, 2019). "It has been reported that Krt5+ and Sox2+ basal progenitors can act as the cellular origin for murine foregut tumor formation." (PMID 31110179, 2019). "Our immunohistochemical examination of skeletal proteins also suggested that the appearance and distribution of the immunomarkers, β-catenin, keratin 5, and vimentin, are dependent on tumor progression." (PMID 30652068, 2018). "Tumors also exhibited rearrangement of cytoskeletal proteins, including β-catenin, keratin 5, and vimentin, depending on tumor progression." (PMID 30652068, 2018). "Important, while the cancer stem like cells coexpressed cytokeratin-5 and -7, the large majority of tumor cells generated in xenografts are either cytokeratin-5+ or cytokeratin-7+, with <10% of the cells remaining double positive." (PMID 30060526, 2018). "Disruption of the ductal architecture by the tumor cells was quantitated based on cytokeratin 5 stainings for myoepithelial cells in primary tumors of 4T1 + RAW264.7 and 4T1 inoculated mice." (PMID 30111338, 2018).
tumor (continued). "High expression of all investigated PDGF family members correlated to increasing NHG and high Ki67, and also to different degrees to TNBC, expression of cytokeratin 5/6 (CK5/6+), young age (< 50 years), large tumour size, ER−, PR− and EGFR+." (PMID 29380207, 2018). "This was supported molecularly by stratified expression of basal urothelial markers; for example, KRT5 expression and proliferation limited to the basal and suprabasal layers, and high tumor‐cell expression of FGFR3 in all cell layers." (PMID 29791078, 2018). "The basal marker, which displayed the highest number of stained tumor cells, was KRT5, with between 70 and 90% of the tumor cells positive for KRT5." (PMID 30550540, 2018). "To address this possibility, we performed tumor induction time course experiments using keratin 5 expression as a marker of stratified squamous epithelial cells." (PMID 29113290, 2017). "Even at the incipient tumor stage, we detected keratin 5 positive cells in regional lymph nodes of all mice." (PMID 29113290, 2017). "Basal cytokeratin 5 expression was used to confirm a reduction of basal cells in tumor-containing sections." (PMID 28402333, 2017). "We found that younger age at diagnosis as well as lymphocytic infiltration and expression of the basal cytokeratin 5/6 in the tumor significantly increased the likelihood that a TNBC was associated with a BRCA1 mutation." (PMID 28721372, 2016). "Expression of both cytokeratin 5 (CK5) and p63, cellular markers of basal cells in the bladder urothelium, is detected in tumor cells of UCC lesions." (PMID 26862755, 2016). "Expression was compared by signal intensity in microarrays and staining of histological sections of these tumours using antibodies to p63, Krt5, Krt7 and Vil1." (PMID 26783136, 2016). "Tumor cell lines derived from xenografts also retained cytokeratin 5 expression suggesting the presence of tumor cells with epidermoid differentiation, along Vimentin expression, which are commonly observed in MEC." (PMID 27285758, 2016). "The best prediction model used node invasion, the size of the tumor, cytokeratin 5/6 expression status and miR-548c-5p." (PMID 26490435, 2015). "Immunohistochemical analysis showed tumor cells diffusely positive for cytokeratin 8/18 and calretinin and focally positive for cytokeratin 5/6 and Wilms’ tumor 1, e-cadherin, and human bone marrow endothelial-1." (PMID 25849448, 2015). "Immunohistochemically, the tumor expressed markers of squamous cell differentiation, such as p63, cytokeratin 5/6, and high-molecular-weight keratin." (PMID 24639909, 2014). "In doing so, we found that Wnt5a suppresses MMTV-Wnt1-induced tumor formation and redirects the tumors that form to a less basal-like phenotype as measured by reduced expression of keratin 5 (K5) and keratin 6 (K6)." (PMID 25401739, 2014). "We also analyzed the expression of cytokeratins in the same set of tumor and find, using unsupervised clustering, that tumors with ARID1A loss of expression are generally KRT5/6-low." (PMID 23650517, 2013). "Basal cytokeratin 5 staining was restricted to the basal cells in the normal ducts, with occasional positive cells observed within tumor masses in all tumors." (PMID 24015230, 2013). "The tumor showed diffusely positive reactivity with cytokeratin (Pan), cytokeratin 19, cytokeratin 5/6, cytokeratin 7, EMA, vimentin, CD56, and NSE and also showed variable reactivity with glial fibrillary acidic protein (GFAP) and VEGF." (PMID 22472343, 2012). "This tumor we report was positive for cytokeratin (Pan), cytokeratin 19, cytokeratin 5/6, cytokeratin 7, and epithelial membrane antigen, so it is easy to differentiate them by immunohistochemistry." (PMID 22472343, 2012). "At the messenger RNA level, such tumours have a relatively high expression of a number of markers, including cytokeratin 5 and 17, EGFR, KIT, laminin, collagen type XVII, calponin 1 and calveolin 2, and a relatively low expression of ER or HER2." (PMID 22276059, 2011).
tumor (continued). "Immunohistochemical analyses of these tumors have shown that the tumor cells frequently express KRT5/6, EGFR and KIT." (PMID 17910759, 2007). "Comparing the molecular subtype of analyzed tumor organoid lines to the histology of their primary tumors, we found that in 8/9 cases, protein expression patterns of KRT5/6 (basal marker protein) and Galectin4 (classical marker protein) mirrored the PurIST results." (PMID 40296444, 2025). "Only few reports have described adenosquamous tumors of the colon with KRT5 positive expression." (PMID 39011470, 2024). "For that, GFP-expressing 4K5 cells (derived from a BC tumor developed in a DKO mouse injected with adenoviruses expressing Cre-recombinase under the control of keratin 5 promoter) were subcutaneously injected in the flank of syngeneic mice and treated with CM-1758 and/or PD-L1 blockade." (PMID 38172127, 2024). "Furthermore, Krt5 itself was primarily expressed in these adjacent normal regions, with very few Krt5-expressing cells within the main tumor." (PMID 36859337, 2023). "Besides the varied expression of markers indicative of malignant tumour behaviour in malignant cells, our study also revealed distinct expression patterns of different keratins, namely, KRT5 and KRT19, at the transcriptome level in epithelial cells." (PMID 37349991, 2023). "However, the percentage of tumors with cytokeratin-5/6 positivity in the basement membrane (BM; a surrogate for tumor invasion) was reduced by treatment with either JBS2, lapatinib, or JBS2 + lapatinib." (PMID 35267611, 2022). "Besides, the mRNA and protein expression of KRT5 were induced in tumor tissues compared with normal tissues." (PMID 35302673, 2022). "This was required since Krt5+ tumor cells were detected in KPGEMM." (PMID 33738287, 2021). "AR (p = 0.053) and KRT5 (p = 0.029) mRNA expression was negatively correlated with tumor grade." (PMID 34209360, 2021). "In contrast, the tumor cells tested negative for p63, p40, smooth muscle actin, S-100, cytokeratin 5/6, thyroglobulin, BRAF V600E, and Epstein-Barr virus-encoded small RNAs." (PMID 32438756, 2020). "However, luminal tumors occasionally showed a linear layer of KRT5/6 positive cells outlining the tumor nests." (PMID 32546765, 2020). "To determine whether Pten-deficient neoplasia was specifically dependent on the BMP5 ligand, we inactivated both Pten and Bmp5 in KRT5-positive basal cells of the prostate and skin." (PMID 32894216, 2020). "Interestingly, while some tumor cells in the metastatic lesions of SKO cells still retained keratin 5 (CK5), an undifferentiated marker of basal lineage, some cells in these lesions activated expression of keratin 8 (CK8), a marker of luminal cells." (PMID 30038266, 2018). "However, when we examined invasive cancer from mice that had been euthanized for tumor burden, there was a considerable overlap between Krt5 and GFP signals." (PMID 29782499, 2018). "In addition, all specimens were also stained with the IHC antibodies specific for MPM, such as calretinin, cytokeratin 5/6, and vimentin, to confirm that tumor antigenicity was completely maintained." (PMID 29755688, 2018). "This kind of cell-specific context-dependency is also reflected in the present study, where we show that CAV1 expression has strong inverse correlation with E-cadherin in KRT5-negative tumour cells, but weak positive correlation in KRT5-positive prostatic glands, which are mostly benign." (PMID 29402961, 2018). "Interestingly, we observed that the presence of OvCa+/CD45– CTCs detected in protocol B was associated with low KRT5 and KRT7 gene expression levels in the paired primary tumor tissue samples." (PMID 29290959, 2017).